DISP3 (dispatched RND transporter family member 3)
Description:
Plays a role in neuronal proliferation and differentiation. Plays a role in the accumulation of cellular cholesterol (By similarity). Involved in intracellular lipid droplet formation. May contribute to cholesterol homeostasis in neuronal cells (By similarity).
Synonyms: KIAA1337; PTCHD2
Tractability: Antibody: UniProt predicts a signal peptide or a membrane-spanning region.
Gene: Protein-coding gene on chromosome 1 (11,478,905 to 11,537,583, forward strand). Ensembl gene ENSG00000204624.
Subcellular location: Endoplasmic reticulum membrane; Nucleus membrane; Cytoplasmic vesicle membrane
Subcellular location (Human Protein Atlas): Nucleoplasm; Cytosol
Gene Ontology:
Biological process: negative regulation of neuron differentiation; positive regulation of lipid metabolic process; positive regulation of neural precursor cell proliferation; cholesterol homeostasis; regulation of lipid transport; smoothened signaling pathway
Cellular component: cytoplasm; endoplasmic reticulum membrane; cytoplasmic vesicle membrane; endoplasmic reticulum; membrane; nuclear membrane
Genetic constraint (gnomAD): Loss-of-function variants: 101 observed, 134.48 expected, observed/expected ratio (o/e) 0.75, 90% interval 0.64 to 0.89. The upper end of that interval is the gene's LOEUF score, 0.89, which puts it in group 3 of 6, group 1 being the genes least tolerant of losing a copy. Missense variants: 1,711 observed, 1,910.4 expected, observed/expected ratio (o/e) 0.9, 90% interval 0.86 to 0.93. Synonymous variants: 856 observed, 832.25 expected, observed/expected ratio (o/e) 1.03, 90% interval 0.97 to 1.09.
Homologues: Orthologues: chimpanzee DISP3 (99% identical), macaque DISP3 (98% identical), pig DISP3 (92% identical), dog DISP3 (90% identical), guinea pig DISP3 (89% identical), rat Disp3 (89% identical), mouse Disp3 (89% identical), tropical clawed frog disp3.2 (68% identical), zebrafish disp3 (53% identical), Caenorhabditis elegans ptc-1 (10% identical), Drosophila melanogaster ptc (9% identical), Drosophila melanogaster Ptr (9% identical), and 3 more. Paralogues in human: NPC1L1 (14% identical), NPC1 (12% identical), PTCH2 (12% identical), PTCH1 (12% identical), PTCHD3 (10% identical), DISP1 (10% identical), PTCHD4 (9% identical), DISP2 (9% identical), PTCHD1 (9% identical), SCAP (7% identical).
Diseases named in the same sentence as DISP3 in open-access papers:
DISP3 is named in the same sentence as 6 diseases in open-access papers, as found by Europe PMC text mining. Sharing a sentence is not in itself a finding about the gene and the disease. The quoted sentences say what the papers report.
prostate carcinoma (1 paper, 2022). A carcinoma that arises from epithelial cells of the prostate gland. "By overlaying Micro-C signals with RNA-seq signals, we noted that the ARID1A gene, which was reported to be dysregulated in prostate tumors, was lowly expressed in C42B prostate cancer cells while the DISP3 gene was not expressed." (PMID 36544209, 2022).
DISP3 also shares sentences with these, for which no sentence is quoted: cancer (1 paper); medulloblastoma (1); mucosal melanoma (1); myopia (1); prostate tumors (1).